ROBO1 (roundabout guidance receptor 1)
Diseases named in the same sentence as ROBO1 in open-access papers (continued):
Sharing a sentence is not in itself a finding about the gene and the disease.
tumor (continued). "Slit guidance ligand 2 (Slit2), a tumor suppressor gene, was found to play diverse roles in apoptosis, neurogenesis and angiogenesis of many malignancies by binding to its receptor Robo1 and then transducing the intracellular signaling." (PMID 33621954, 2021). "In vivo results confirmed the anti-tumor effects of NONHSAT024778 knockdown activating miR-1290 to inhibit the oncogene Robo1." (PMID 33767589, 2021). "We previously reported that radioimmunotherapy (RIT) using 90Y-labeled anti-ROBO1 IgG (90Y-B5209B) achieved significant anti-tumor effects against small-cell lung cancer (SCLC) xenografts." (PMID 33086574, 2020). "The tumor uptake of 111In-anti-Robo1 antibody reached a maximum of 15.0 ± 0.69% ID/g at 48 h after injection and remained high for an extended period of time in HepG2 xenografts." (PMID 32256588, 2020). "It has been reported that the Slit2/Robo1 signal in cancer plays an important role in invasion, migration, the epithelial-mesenchymal transition, as well as tumor-induced angiogenesis." (PMID 32256588, 2020). "Slit2, a secreted protein, interacts with its receptor Robo1 to regulate the differentiation of intestinal stem cells and participate in inflammation and tumor development." (PMID 32398956, 2020). "Based on current knowledge, ROBO1 plays either a tumor suppressor or a promoter role, depending on the tissue involved and type of cancer." (PMID 32807784, 2020). "If the activity of Robo1 is blocked it will reduce the microvascular formation and reduce the tumor volume of human malignant melanoma A375 cells." (PMID 32670371, 2020). "Robo1 is known to be expressed in fetal tissues, especially in the nervous system, and was originally reported as a tumor-specific antigen in liver cancer." (PMID 32256588, 2020). "Our work implicates a novel role for SLIT-ROBO signaling in CSC and shows a new mechanism by which Id proteins control the self-renewal phenotype by suppressing the Robo1 tumor suppressor role in TNBC." (PMID 32766238, 2020). "Slit2 binds to Robo1, which is mainly expressed in tumor cells, and its important role in the regulation of tumor growth and metastasis in CRC has been extensively studied." (PMID 31242633, 2019). "This study suggests that activation of Slit2/Robo1 signaling in CRC induces tumor metastasis partially through activation of the TGF-β/Smads pathway." (PMID 31242633, 2019). "Slit2 binds to Robo1 in tumor cells, and plays an important role in the regulation of tumorigenesis and metastasis." (PMID 31242633, 2019). "Our study confirmed that SLIT2 and ROBO1 are upregulated in OS; inhibiting SLIT2/ROBO1 signaling by the silencing of ROBO1 or SLIT2 produced an anti-tumor effect." (PMID 29523788, 2018). "Recently, an increasing number of studies have found that the SLIT2/ROBO1 signalling pathway is closely involved in tumourigenesis by inhibiting the proliferation, migration, and invasion of tumour cells." (PMID 29743814, 2018). "Slit/Robo signalling has been shown to interact with the Wnt/β-catenin signalling in different types of tumour cells, and we found here that Robo1/2 KO pancreatic cells exhibit a reduced level of Axin2 expression but Lef1 appeared unchanged at E12.5." (PMID 30504829, 2018). "The vast majority of PDAC tumours were positive for ROBO1 (106/109) with 55% of patients presenting high expression of ROBO1 (score ≥200 in 60/109 samples)." (PMID 30504844, 2018). "We also demonstrate that in PDAC patients, high ROBO1 mRNA expression inversely correlates with tumour epithelial cellularity and positively correlated with markers of activated stroma, as well as with Wnt and TGF-β pathways." (PMID 30504844, 2018). "The stable ROBO1-knockdown group exhibited a significant delay in the growth of the xenografted tumor and a reduced tumor burden as compared with the control group." (PMID 29523788, 2018). "RNA sequencing (RNAseq) confirmed that ROBO1 was highly expressed in tumours from this cohort, while ROBO2 expression is much lower." (PMID 30504844, 2018).
tumor (continued). "As we observed, ROBO1 is highly expressed in most of the tumor cell lines, and in HCC tissues, the expression ROBO1 is extremely high within a reliable confidence interval." (PMID 28977866, 2017). "Then, CCLE database was utilized to further validate the expression characteristic of ROBO1 in differential tumor cell lines." (PMID 28977866, 2017). "Among the tumor specimens, 78.26% (18/23) of the cases presented high level ROBO1, and only 21.74% (4/17) cases showed relatively lower RGS3 expression." (PMID 28977866, 2017). "In this study, we confirmed that srGAP1 binds to Robo1 in responding to the Slit2 treatment and mediates its tumor suppressive function in CRC." (PMID 27923383, 2016). "Conversely, the tumor suppressor miR-218 promotes invasion and metastasis by targeting Robo1, and thereby activating the Slit/Robo1 signaling pathway." (PMID 27322246, 2016). "All these results indicated that tumor cells with low Slit2/Robo1 expression potentially had metastatic intention." (PMID 26400100, 2015). "Administration of 90Y-labeled anti-ROBO1 IgG (90Y-anti-ROBO1 IgG) showed significant antitumor effects, such as tumor growth suppression in ROBO1-positive HCC xenografts." (PMID 26017283, 2015). "The tumor tissues from the ApcMin/+;Slit2 mice showed an increased co-localization of Slit2/Robo1 compared to the tumor tissues derived from the ApcMin/+ mice." (PMID 25605242, 2015). "Robo1 is mainly present in tumor cells, whereas Robo4 is located primarily in endothelial cells of tumor vessels in CRC." (PMID 25605242, 2015). "Co-localization of Slit2/Robo1 was also seen in the tumor tissues from the DMH/DSS induced Slit2-Tg (DMH/DSS-Slit2) mice." (PMID 25605242, 2015). "Ectopic expression of Slit2 activated Slit2/Robo1 signaling and promoted tumorigenesis and tumor growth." (PMID 25605242, 2015). "The tumour uptake of 111In-anti-ROBO1 was 4.68 ± 1.8, 9.22 ± 1.5, 15.0 ± 0.69, 11.5 ± 4.3, 12.6 ± 1.6, and 6.73 ± 1.1% ID/g at 6, 24, 48, 72, 144, and 240 h after injection, respectively." (PMID 25006547, 2014). "The maximal tumour uptake of 111In-anti-ROBO1 occurred at 48 h after injection and then decreased slowly." (PMID 25006547, 2014). "90Y-anti-ROBO1 showed significant tumour growth suppression, indicated by the measurement of tumour volume, and we observed pathological changes, such as cell degeneration and an increase in apoptotic cells." (PMID 25006547, 2014). "The tumour uptake of 111In-anti-ROBO1 MAb in HepG2 xenograft mice was 15.0% ± 0.69% injected dose per gram at 48 h after injection." (PMID 25006547, 2014). "In this report, we demonstrate antitumour effects of 90Y-anti-ROBO1 on xenograft tumours in nude mice." (PMID 25006547, 2014). "90Y-anti-ROBO1 significantly suppressed tumour growth, compared with saline and cold-anti-ROBO1 treatment." (PMID 25006547, 2014). "Decreased miR-218 levels eliminated Robo1 repression, which activated the Slit-Robo1 pathway through the interaction between Robo1 and Slit2 to trigger tumor metastasis." (PMID 23768087, 2013). "Within tumours, ROBO1 expression increases towards the invasion front, and is inversely proportional to the expression of N-cadherin." (PMID 23818228, 2013). "In contrast, our data suggests that increased tumour invasion is mediated by a change in N-cadherin dynamics, mediated through ROBO1 by ZEB1." (PMID 23818228, 2013). "Multiparous (≥5) women with altered SLIT2 and ROBO1 along with advanced tumor stage (III/IV) and early sexual debut (<19 years) had worst prognosis." (PMID 22719878, 2012). "miR-218 has also been shown to affect cancer progression by inhibiting tumor cell migration and metastasis via the repression of the Slit2/Robo1 pathway in gastric and in nasopharyngeal tumors, respectively." (PMID 23226307, 2012). "To investigate this further, we performed mutation analysis in 1781T of protein coding regions and intron/exon splice junction sites of the top 3p12-pcen tumour suppressor gene candidates, ROBO1, GBE1 and VGLL3." (PMID 22163003, 2011).
tumor (continued). "The marker genes Myc, Glul and Oat presented pre-tumor-specific differential expression which was reverted in the tumor state, whereas Ccnd1, Gpc3, Mvk, Pparg, Rbl2, Robo1 were only upregulated in tumors." (PMID 21464922, 2011). "The subsequent analysis in primary MCL identified five genes (SOX9, HOXA9, AHR, NR2F2, and ROBO1) frequently methylated in these tumours." (PMID 21603610, 2011). "Our data indicate that Src activates the Abl kinase, which in turn, stabilizes the expression of Robo1 and increases GTPase activity to promote tumor cell migration." (PMID 21301049, 2010). "Here, we describe a molecular relationship between Src, Abl, and Robo1 that promotes tumor cell migration." (PMID 21301049, 2010). "Decreased miR-218 levels eliminate Robo1 repression, which activates the Slit-Robo1 pathway through the interaction between Robo1 and Slit2, thus triggering tumor metastasis." (PMID 20300657, 2010). "The restoration of miR-218 suppresses Robo1 expression and inhibits tumor cell invasion and metastasis in vitro and in vivo." (PMID 20300657, 2010). "In contrast, knockdown of Robo1 gene expression by RNAi had an effect on reducing tumor cell invasion similar to that of the restoration of miR-218, although Robo1 knockdown alone demonstrated a weak effect." (PMID 20300657, 2010). "Robo1 has been shown to be over-expressed in cancer cells and is known to promote tumor angiogenesis and metastasis via an interaction with Slit." (PMID 20300657, 2010). "Here, we provide evidence that Robo1 plays an important role in tumor cell migration induced by Src and Abl." (PMID 21301049, 2010). "In liver tissues, differential expression of ROBO1, ROBO4 and SLIT2 was found to be associated with clinicopathological parameters such as tumor staging and differentiation." (PMID 19114000, 2008). "Accordingly, only ROBO1 was found to be significantly overexpressed in tumor tissues (MeanNormal = 0 ± 0.63, MeanTumor = 1.57 ± 1.63; p = 0.011)." (PMID 19114000, 2008). "Although only a limited number of clinical trials have evaluated CAR-NK products based on NK92, PB-NK, and UCB-NK cells, there is growing interest in targeting common tumor antigens like Roundabout homolog 1 (ROBO1), NK cell-activating receptor (NKG2D), MSLN, HER2, and MUC1." (PMID 40299429, 2025). "Reported to promote anti-tumor activities upon ROBO1 knockout/knockdown." (PMID 40429844, 2025). "Conversely, deubiquitinating and stabilizing ROBO1 in CRC can inhibit tumor migration." (PMID 38081962, 2024). "In contrast to Robo1 and Robo3, Robo2 primarily functions as a tumor suppressor." (PMID 38081962, 2024). "Furthermore, the tumour burden of PANC-1 cells in the subcutaneous xenograft model was significantly reduced after stable knockdown of ROBO1 as well as in the liver metastasis mouse model mentioned before." (PMID 36792623, 2023). "Based on marker genes for every cluster, we revealed one set of lymphatic endothelial cells (cluster 9, TFF3 +) and nine sets of vascular endothelial cells (FLT1 +): One was mostly interface-derived (clusters 2; HLA-DQA2 +) and three were mostly tumor-derived (clusters 4, 6 and 8; ROBO1 +)." (PMID 37644609, 2023). "In WT mice, ROBO1-FL-expressing tumour cells displayed a predominant population in liver metastatic niches, especially in Kpc1199Mix-I-modelled cells, during coadaptation with hepatocytes, while in Slit2/CKO mice, Kpc1199CTRL cells outcompeted Kpc1199Robo1-FL cells in the absence of SLIT2." (PMID 36792623, 2023). "To explore why ROBO1 is enriched in liver metastases and how SLIT2-ROBO1 manipulates the selection of tumour cells in coadaptation, we next used a cell mixture composed of 50% Panc02Robo1-FL and 50% Panc02CTRL cells (PG0) in an intrasplenic injection mouse model." (PMID 36792623, 2023). "SLIT2 overexpression or the deletion of ROBO1 restricts tumor growth in vitro and in vivo." (PMID 35838343, 2023).
tumor (continued). "Overall, we show that Slit2/Robo1 signaling is tumor suppressive in SCLC, suggesting that Slit2 may represent an ideal substrate for the development of an immune‐based therapeutic agent." (PMID 35838343, 2023). "Moreover, SLIT2 and ROBO1 have also been reported to inhibit tumor metastasis by reducing cell adhesion and increasing cell migration and metastasis." (PMID 37238655, 2023). "Multiple microRNAs have been shown to control Slit2 and Robo1 post-transcription in tumor cells." (PMID 37238655, 2023). "Additionally, mir-203 targets roundabout guidance receptor 1 (ROBO1) mRNA, which codes for a well-known tumor suppressor, thus possessing opposite effects than those of the ZNF217 oncogene." (PMID 36551531, 2022). "Beyond Sema4F, multiple axon-related molecules, classified for their function in tumor axonogenesis, such as Bmp7, Robo1, Fibronectin, or Nrp1, and the synaptic adhesion molecule IGSF11/VSIG-3 are regulated upon TGFβ−mediated EMT induction, hnRNP E1 silencing, or Platr18 overexpression." (PMID 34810279, 2022). "Furthermore, OLFML3 is a potential target gene of ROBO1, and its inhibition restores the lost tumor-suppressing effects of ROBO1E280*." (PMID 35615148, 2022). "In HCC, ROBO1 is up-regulated in tumour tissues and is one of the poor-prognosis-related and immune-related genes that may contribute to hepatic carcinogenesis." (PMID 35236289, 2022). "Taken together, these results suggested that ROBO1 may act as a tumor suppressor and potential prognostic marker for CCA." (PMID 35615148, 2022). "Nevertheless, an increasing number of studies indicated that the ROBO1 pathway may function as a tumor suppressor in a variety of malignancies." (PMID 35615148, 2022). "Besides these, the univariable analysis showed that ROBO1 expression, histological grade, tumor thrombus, nerve invasion, N stage, and clinical stage were significantly associated with the OS of CCA patients." (PMID 35615148, 2022). "ROBO1 modulates the chemotaxis of T cells and tumor angiogenesis to counteract the tumor growth." (PMID 34025641, 2021). "The Slit2/Robo1 signaling pathway was reported to participate in the tumor progression of CC." (PMID 33621954, 2021). "Compared with those from the control cells, the tumor generated by Robo1 re-expression in siNONHSAT024778 cells was significantly larger in size and weight, whereas the tumor generated by Robo1 re-inhibition in Lv-NONHSAT024778 cells was significantly smaller in size and weight." (PMID 33767589, 2021). "Importantly, downregulated Slit2/Robo1 signaling is reported to suppress the tumor progression by regulating beta-catenin." (PMID 33621954, 2021). "Moreover, its expression increased in parallel with the tumor stage, and Robo3 levels correlated negatively with those of Robo1 and Robo2." (PMID 32670371, 2020). "The tumor suppressor ROBO1 is a robust example of key genes that can be hampered by this process." (PMID 32778592, 2020). "In addition, IHC results showed that normal liver tissue stained negatively or weakly positive for BIRC5 and ROBO1, while tumor tissue was high or medium positive." (PMID 33195412, 2020). "Recurrent variants (p.R119Q and p.R131C of ROBO1 and p.R462C, p.A340T, p.P322L, p.R461C, p.R388W, p.R420W, and p.G576R of SLIT2) found that implies the pathogenic significance of the variants across tumour types." (PMID 33318575, 2020). "Specific blockage of Slit2 binding to Robo1 could inactivate TGF-β/Smads signaling, although whether TGF-β/Smads signaling is involved in Slit2/Robo1-induced tumor growth and metastasis of CRC is still to be demonstrated." (PMID 31242633, 2019). "The blocking of Slit2/Robo1 signaling may suppress tumor metastasis by the partial inactivation of the TGF-β/Smads pathway." (PMID 31242633, 2019). "Herein, we speculate that the blocking of Slit2/Robo1 signaling inhibits tumor metastasis through the targeting of TGF-β1." (PMID 31242633, 2019).
tumor (continued). "Additionally, SLIT2/ROBO1 signalling has been shown to inhibit tumour cell proliferation and migration." (PMID 29743814, 2018). "Our findings provide a novel insight into the biology of OS progression and raise the possibility that targeting the SLIT2/ROBO1 axis could be a beneficial clinical anti-tumor strategy for OS patients." (PMID 29523788, 2018). "High levels of Robo1 in the tumour stroma could on their turn modulate Wnt pathway activation in response to TGF-β activation." (PMID 30504844, 2018). "Furtherly, we recognized that miR-218, a tumor suppressor, might be an upstream regulator for ROBO1 directly binding to the mRNA 3’UTR and potentially modifying the expression and function of ROBO1." (PMID 28977866, 2017). "Tumor primary from liver indicates a reliable higher expression of ROBO1 among the 37 tumors." (PMID 28977866, 2017). "Therefore, we determined that a more radiosensitive tumor than HCC would be an appropriate therapeutic target for 90Y-anti-ROBO1 IgG." (PMID 26017283, 2015). "The Slit2/Robo1 signaling can induce precancerous lesions of the intestine and tumor progression." (PMID 25605242, 2015). "Furthermore, they demonstrated the neutralization of ROBO1 reduced the microvessel density and the tumor mass of human malignant melanoma A375 cells in vivo." (PMID 26674478, 2015). "As a result of the biodistribution study, we observed tumor uptake of 111In-anti-ROBO1 IgG." (PMID 26017283, 2015). "ROBO1 is a membrane protein that contributes to tumor metastasis and angiogenesis." (PMID 26017283, 2015). "In the RIT study, 90Y-anti-ROBO1 IgG significantly reduced tumor volume compared with baseline." (PMID 26017283, 2015). "Previous reports indicate that ROBO1 contributes to tumour metastasis and angiogenesis." (PMID 25006547, 2014). "Tumours in the right flank and liver showed high accumulation of 111In-anti-ROBO1." (PMID 25006547, 2014). "Therefore, the results confirm that 111In-anti-ROBO1 specifically targets ROBO1, and it is expected that 90Y-anti-ROBO1 would accumulate in ROBO1-positive tumours because of the similar binding specificity." (PMID 25006547, 2014). "We next tested whether interference with ROBO1 has direct effects on tumour cell migration and invasion." (PMID 23818228, 2013). "Similarly, ROBO1 was found at the invasion front, and its expression was mutually exclusive to that of N-cadherin, which was preferentially at the tumour core." (PMID 23818228, 2013). "ROBO1 belongs to a large, single-pass transmembrane cell surface receptors involved in multiple cell processes, including cell migration, myogenesis, leukocyte chemotaxis and tumor angiogenesis." (PMID 23593148, 2013). "The Cox multivariate analysis indicated that alterations of SLIT2 and ROBO1 along with advanced tumor stage (III/IV), multiparity (≥5) and early sexual debut (<19 years) were determinants of poor prognosis for CACX patients, thereby enabling efficient classification of the high-risk patients." (PMID 22719878, 2012). "Moreover Cox multivariate analysis revealed alterations of SLIT2 and ROBO1, in combination with advanced tumor stage (III/IV), multiparity (≥5) and early sexual debut (<19 years) as determinants of worse prognosis." (PMID 22719878, 2012). "Moreover Cox multivariate analysis revealed that alterations of SLIT2 and ROBO1 coupled with advanced tumor stage (III/IV), multiparity (≥5) and early sexual debut (<19 years) were predictors of poor prognosis for CACX patients." (PMID 22719878, 2012). "Importantly the expression of the SLIT2 and ROBO1 tumour suppressor genes was also enhanced by GRsiRNA transfection (P<0.05)." (PMID 22132142, 2011). "Finally, Ccnd1, Gpc3, Mvk, Pparg, Rbl2, and Robo1 exhibited a tumor-specific response, where adverse expression changes were observed for Pparg, which appeared down regulated in transgenic cells (fold change <0.4) and significantly up regulated in tumors." (PMID 21464922, 2011).